RHOA (ras homolog family member A)
Diseases named in the same sentence as RHOA in open-access papers (continued):
Sharing a sentence is not in itself a finding about the gene and the disease.
cancer (continued). "It is likely that the proliferation of cancer cells was more dependent on geranylgeranylated proteins such as RhoA, Rac1, etc., leading to greater sensitivity to the depletion of GGPP and inhibition of GGTase-Iβ expression than in the non-cancer cells." (PMID 28481295, 2017). "More recently, it has been demonstrated that human CAFs secreted ADAM10-rich exosomes that promoted cell motility and activated RhoA and Notch signaling in several cancer cells." (PMID 28121625, 2017). "Inhibiting HDAC1 enhanced the anti-cancer effects of statins through downregulation of GGTase-Iβ expression, and thus further inactivation of RhoA." (PMID 28481295, 2017). "Cdc42 stimulates filopodia formation, RhoA induces the formation of stress fibers, and Rac1 induces lamellipodia formation, all of which play critical roles in cancer cell invasion and metastasis." (PMID 28423650, 2017). "RhoA, B and C, members of the Rho group of GTPases, have very well- described roles in cancer progression." (PMID 28212429, 2017). "Here the authors show that platelets improve anoikis resistance of cancer cells and increase metastasis by activating Yap through a RhoA/MYPT-PP1 pathway." (PMID 28827520, 2017). "RhoA was determined as the key target for the enhancement of statin-induced anti-cancer effects by HDAC1 inhibitor." (PMID 28481295, 2017). "As a consequence, the inhibition of Rab, Ras, and RhoA has a strong effect on cancer patients through various mechanisms such as inducing apoptosis, cell cycle arrest, anti-migration, anti-invasive, and antiangiogenic effects." (PMID 28809381, 2017). "It was proposed that enhanced RhoA activity facilitates PDPN-positive-fibroblasts to create a microenvironment promoting cancer growth." (PMID 28938000, 2017). "Here, we demonstrate that exosomes derived from cells with high metastatic potential can modulate phenotypic plasticity in less aggressive cancer cells and elicit structural alterations of endothelial cells in a RhoA/ROCK dependent fashion." (PMID 28680152, 2017). "There is also substantial evidence that activation of Rac1, Cdc42 and RhoA is necessary for the metastatic behavior of cancer cells." (PMID 28289332, 2017). "Platelet interaction with cancer cells led to activation of RhoA and YAP1 dephosphorylation via the PP1-MYPT1 phosphatase which induced nuclear localization of the protein." (PMID 28827520, 2017). "In contrast, co-transfection with TSB2, which blocks target site 2, dose-dependently increased expression of RhoA mRNA in HT-29 carcinoma cells transfected with AntagomiR-155-5p, suggesting that miR-155-5p interacts with this specific target site in RhoA mRNA." (PMID 28146427, 2017). "We found that inhibition of miR-155-5p decreased RhoA activity and migration of HT-29 carcinoma cells in response to CCL17 stimulation." (PMID 28146427, 2017). "As a key member of the Rho GTPase family, RhoA is known to be involved in proliferation, migration, invasion, apoptosis, and angiogenesis, in several types of cancers." (PMID 27888624, 2016). "Like many other members in Rho GTPases family, increased RhoA expression has often been correlated with human cancer progression through its regulation of cell migration and is linked to poor prognosis." (PMID 26816343, 2016). "Elevated levels of RhoA expression are observed in numerous forms of cancer, most notably in breast, colon, and lung cancers." (PMID 27304967, 2016). "Here, we identified the SCN4B gene as an important modulator of RhoA activity and invasiveness in cancer cells." (PMID 27917859, 2016). "This study is the first to demonstrate that aberrantly expressed C5aR promotes the conversion of RhoA-GDP to RhoA-GTP in cancer cells, which induces their cytoskeletal rearrangement and increases their invasive ability." (PMID 27756879, 2016).
cancer (continued). "Ect2, which has activity for multiple members of the Rho GTPase family including RhoA, Rac1 and Cdc42, has been recognized as an oncogene in human cancer since 2010, being aberrantly overexpressed and mislocalised in various types of tumors." (PMID 27104658, 2016). "Six tumors with mutant RHOA (27 %) were early cancers (T1), whereas the other 16 tumors (73 %) were advanced cancers (T2–T4)." (PMID 25823974, 2016). "Specifically, RhoA activity in cancer cells is thought to be stimulated by macrophage contact and leads to the formation of invadopodia." (PMID 27158478, 2016). "In human cancers, RhoA activation and its expression must be tightly regulated for appropriate cellular migration." (PMID 27713154, 2016). "As TGF-β mediated Rac1/RhoA activation was reported to be involved in cancer metastasis, these inhibitors can be possible therapeutic reagents." (PMID 27027347, 2016). "It indicates that, in addition to membrane transport proteins and survival, cancer stem cells/SP cells are also regulated by RhoA and contribute to drug resistance of CRC." (PMID 27888624, 2016). "Loss of p120 expression, a common feature of invasive cancers, therefore not only destabilizes cadherin-dependent cell–cell adhesion, but also induces multinucleation and CIN by introducing RhoA-dependent cytokinesis defects." (PMID 28004812, 2016). "RhoA GTPase is overexpressed and overactivated in cancer and is involved in cancer progression, directly regulating cell proliferation, survival, and invasion." (PMID 26649141, 2016). "In contrast, RhoA/ROCK activation in stromal cells surrounding cancer stem cells increased stiffness of extracellular matrix leading to increased stem cell adhesion to extracellular matrix and consequently increased spreading, migration, and proliferation." (PMID 26725045, 2016). "Although Rac1/Cdc42 and RhoA have antagonistic functions, their coordination of their activities is essential for cell motility and cancer metastasis." (PMID 27384474, 2016). "Our results show that dual inhibition of polo-like kinase 1 and RhoA/Rho kinase (ROCK) leads to the synergistic effects in KRAS-mutant cancers." (PMID 27193833, 2016). "On the other hand, recent observations have revealed that small-molecule inhibitors targeting RhoA, such as Rhosin and Y16, not only suppress the cellular motility, but also suppress the proliferative activity of cancer cells in vitro." (PMID 27145964, 2016). "In accordance with the observation found in association with ARHGEF15 depletion, both the RhoA inhibitor and RhoA gene silencing reduced the proliferative activity, migration and invasiveness of the cancer cells." (PMID 27145964, 2016). "In particular, we show here that chemokine signaling, focal adhesion, and other cancer-related (Cluster 6, 17, 20, 26 and 31) pathways, all involve RHOA." (PMID 27806312, 2016). "Together, these findings support that GPR55 activation elicits pro-invasive responses in cancer cells by binding to Gq/11 heterotrimeric G proteins and activating RhoA." (PMID 27340777, 2016). "Wnt proteins induce cancer cell growth, migration and invasion, through the activation of β-catenin and RhoA signaling pathways." (PMID 27333045, 2016). "RhoA, in particular, is activated in several human cancers and is reported to be involved in cancer progression and metastasis." (PMID 27145964, 2016). "In conclusion, this new signaling pathway of VEGF-A/NRP1 induced cancer cell proliferation by forming a GIPC1/Syx complex that activated RhoA to degrade the p27 protein." (PMID 26209534, 2015). "In multiple melanomas, SDF-1α increases homing, adhesion and invasiveness of cancer through the activation of GTPases of the Ras superfamily, RhoA and Rac1." (PMID 26231656, 2015). "Our findings are in harmony with previous reports that SKP2 has a critical pro-oncogenic function for the development and progression of cancers including PCa, through affiliating oncogenic signaling pathways such as RhoA, c-Myc and Ras." (PMID 25596733, 2015).
cancer (continued). "Further study confirming our proposed compensatory mechanism is warranted, as is a deeper understanding of the overlapping and differential functions of RhoA, RhoC and other related Rho GTPases in cancer biology." (PMID 26030593, 2015). "In summary, we proposed a novel signal transduction pathway of VEGF-A/NRP1 that induced cancer cell proliferation by forming a GIPC1/Syx complex that activated RhoA and degraded p27." (PMID 26209534, 2015). "These latter findings are reminiscent of (colorectal) cancer cells in which a more rounded morphology as a result of overexpression of RhoA correlated to increased ability to migrate in vitro and metastasize in vivo." (PMID 25811796, 2015). "Focal adhesion kinase (FAK), Src, myosin light chain (MLC) and RhoA activations are important for cancer motility." (PMID 25868853, 2015). "A treatment with a cell-penetrating peptide designed to inhibit interactions between GIPC1 and Syx suppressed the activation of RhoA as well as cancer cell proliferation." (PMID 26209534, 2015). "RhoA activation status downstream of actin cytoskeleton dynamics is a key regulator of E-cadherin expression in these cancer cells." (PMID 25756282, 2015). "The effects of RhoC/ROCK depletion on cancer cell:EC interaction are thus different from RhoA depletion." (PMID 25677806, 2015). "This is consistent with our previous observations that RhoA and RhoC induce distinct phenotypes in cancer cells." (PMID 25677806, 2015). "This indicates that RhoA and RhoC act in different ways to affect cancer cell: EC interaction even though they both contribute to the initial step of cancer cell adhesion to ECs." (PMID 25677806, 2015). "Cytoskeleton is associated with EMT and cytoskeletal reorganization is a prerequisite for cell motility and cancer cell invasion, and members of Rho GTPases including RhoA, Rac1 and Cdc42 play an important role in EMT as well." (PMID 26452029, 2015). "We found that the set of genes regulated by the 11 deregulated miRNAs was enriched for proteins that have key roles in various pathways, such as PTEN/Akt, MAPK, RhoA, FOXO3 and PDCD4 genes, which are causatively deregulated in cancer diseases." (PMID 24788655, 2014). "In doing so, we further uncover the signalling mechanisms driving EphA-mediated cell–cell repulsion and find that signalling from EphA receptors, via the guanine nucleotide exchange factor (GEF) Vav2 to activate RhoA, can stimulate cancer cell–cell repulsion." (PMID 24795148, 2014). "The RhoA/ROCK pathway plays a crucial role in cancer angiogenesis and should also be a potential target for anti-angiogenic therapy." (PMID 25289078, 2014). "RGS16 has been implicated in negatively regulating the MAPK, AKT/PI3K, RhoA, and SDF-1/CXCR4 oncogene pathways in normal or cancer cell lines." (PMID 25568667, 2014). "Consistent with the finding that CIL drives embryonic cell dispersal during development, we show here that EphA receptors mediate CIL via Vav2 and RhoA and that EphA2/EphA4 can regulate cancer cell dissemination from dense cancer cell populations." (PMID 24795148, 2014). "Our findings are consistent with a recent study showing that MT1-MMP cleavage of EphA2 can enhance individual cancer cell invasion via RhoA-mediated repulsive signalling." (PMID 24795148, 2014). "In general, adhesion signaling is poor in dormant cancer cells, and weak adhesion signaling up-regulates RhoA-ROCK signaling." (PMID 24523903, 2014). "RhoA/ROCK signaling has emerged as an attractive target for the development of new cancer therapeutics." (PMID 25238232, 2014). "On immunohistochemical analysis, the cytosolic compartment showed brown staining in most of the cancer cells, indicating high RhoA activity and high ROCK-I and ROCK-II protein levels, while the nuclei showed very weak staining." (PMID 24908363, 2014).
cancer (continued). "RGS16 was of interest to our study for two reasons: 1) RGS16 regulates GPCRs, which are common targets for deregulation in cancer and 2) RGS16 has been linked to regulating the MAPK/RAS, PI3K/AKT, RhoA, and SDF-1/CxCR4 oncogene pathways." (PMID 25568667, 2014). "The RhoA/ROCK pathway participates in the process of angiogenesis in numerous types of cancer, including PCa." (PMID 25289078, 2014). "ErbB-2 phosphorylation and RhoA activation are required for several downstream cellular effects including the promigratory and prometastatic effects of semaphorins on cancer cells and Sema4D-induced axonal growth cone collapse." (PMID 25137062, 2014). "The model provides the first step towards understanding how different levels of the small GTPases, RhoA and Rac1, in a cell govern phenotypic plasticity during carcinoma metastasis under the influence of external signals in the tumor microenvironment." (PMID 25245029, 2014). "Up-regulation of RhoA and RhoC are essential for cell migration and cancer metastasis in various cancers." (PMID 23483935, 2013). "Many of the proteins that are modified by GGTase-I are members of the Ras superfamily of GTPases, including RhoA, Rac, and Cdc42, which play important roles in human cancer." (PMID 23607551, 2013). "Previous studies have found that invasive growth and metastasis were repressed in a variety of cancer cells (including CRC cells) when RhoA activity was inhibited." (PMID 23626715, 2013). "In this review, we focus on the trafficking and cancer-related functions of Cdc42, Rac1 and RhoA in mammalian cells." (PMID 23538840, 2013). "Expression of ARHGAP11A in cancer cells suppressed RhoA-dependent mechanisms, such as stress fiber formation and focal adhesion, which made the cells more prone to migrate." (PMID 24386239, 2013). "RhoA, RhoB and Cdc42 play a crucial role in the development of cancer, being main factors responsible for cellular motility and loss of adhesion." (PMID 23420497, 2013). "In fact, we showed that ARHGAP11A promotes migration and invasion of cancer cells, by inhibition RhoA and resultant counter-activation of Rac1." (PMID 24386239, 2013). "Although RhoA and RhoC share 92% identity, they have markedly different roles in motility and cancer." (PMID 24224016, 2013). "RhoA, ROCK1 and Rac1 proteins are GTPases that regulate F-actin and thereby regulate cancer cell migration and have been implicated in metastasis of several types of cancer including CRC." (PMID 23560089, 2013). "Most of what we know about the role of Rho GTPases in cancer cell invasion comes from the studies of the prototypic members RhoA, RhoB and RhoC, Rac1 and Cdc42." (PMID 22860091, 2012). "Although both vincristine and paclitaxel act on microtubules as anti-cancer drugs, our results indicate that they influence cellular motility differently depending on the effect on RhoA activity." (PMID 23057787, 2012). "The c-Myc–Skp2–Miz1 transcriptional complex has been found to activate RhoA gene and to be critical for cell invasion and cancer metastasis." (PMID 22235332, 2012). "Our cellular data indicated that HTPB inhibited cancer cell migration through inhibiting activity of matrix metalloproteinases, RhoA, integrin-β1 and focal adhesion complex and disrupting F-actin arrangement." (PMID 22279574, 2012). "Some previous studies have revealed that RhoA and RhoC expression are frequently increased in human cancers, while RhoB is often down-regulated." (PMID 22860091, 2012). "It has been shown that the expression of MMPs was regulated by small Rho GTPases (Cdc42, Rac1 and RhoA), which are involved in many normal and pathological cellular processes, including cancer invasion and metastasis." (PMID 22610942, 2012). "In our previous report, we demonstrated that a low dose lovastatin (equivalent to cardiovascular dose) induced G1 phase cell cycle arrest and cell senescence via RhoA modulation in cancer cells." (PMID 23234464, 2012).
cancer (continued). "The c-Myc–Skp2–Miz1 transcriptional complex has been previously shown to activate RhoA and to be essential for cell invasion and cancer metastasis." (PMID 22235332, 2012). "Rnd3 has been shown to regulate cell morphology and migration in cultured fibroblasts and cancer cells by antagonizing RhoA." (PMID 21435554, 2011). "Deleted in liver cancer 1 (DLC1) serves as an important RhoGTPase activating protein (RhoGAP) protein that terminates active RhoA signaling in human cancers." (PMID 21966542, 2011). "For several kinds of cancers, DLC1 down-regulation or deletion was reported to leave the Rho/ROCK/MLC pathway and RhoA GTPase pathway more active, resulting in the cancer cells’ endless proliferation and migration." (PMID 22272086, 2011). "ARHGAP19 is a member of a family of GTPase activating proteins, and other family members, 8, 9, 12 and 15, are expressed in several types of cancer and activate Cdc42, Rac1 or RhoA, small GTPases required for migration." (PMID 21501518, 2011). "A role for RhoA has been shown in regulating cell migration in highly aggressive cancer cells such as MDA-MB-231 and MDA-MB-435." (PMID 21738726, 2011). "In particular, the role of RhoA (Ras homolog gene family, member A), Rac1 (Ras-related C3 botulinum toxin substrate 1) and Cdc42 (cell division cycle 42) in cancer progression induced by each of the three oncogenes is described." (PMID 21943101, 2011). "RhoA is frequently overexpressed in cancer, while depletion of Rac1 strongly inhibits lamellipodia formation, cell migration and invasion in carcinoma cells." (PMID 21943101, 2011). "More importantly, the overexpression of RhoA is often observed in clinical cancers and it has been repeatedly identified as a gene associated with metastasis." (PMID 20429915, 2010). "Transforming growth factor-β1 activates RhoA, which promotes cancer cell invasion and eventually leads to metastasis by disrupting E-cadherin-mediated adherens junctions." (PMID 20145621, 2010). "The reduction of RhoA and RhoC expression by RNA interference (RNAi) resulted growth inhibition of cancer cells." (PMID 20828398, 2010). "This conclusion is in agreement with the previous studies that FAK is a negative regulator of RhoA activity in many human cancers." (PMID 20082722, 2010). "But in the Ad-RhoA-RhoC group, cancer cells showed intense positive staining with smaller cell sizes and contracted nucleus." (PMID 20828398, 2010). "Previously, we have demonstrated that Grp78 enhanced FAK phosphorylation and inhibited RhoA activity in hepatocelluar carcinoma cells." (PMID 20082722, 2010). "The role of Centd1 is not understood, although the protein functions down stream of RhoA to regulate focal adhesion dynamics suggesting an involvement in invasion and metastasis in cancer." (PMID 19194513, 2009). "Many studies have been done in down-regulating the expression of RhoA and RhoC by RhoA or RhoC-specific siRNAs to inhibit the proliferation and invasiveness of cancer cells." (PMID 19374769, 2009). "Blebbing cell motility of human MDA-MB-435 cancer cells in 3D matrice relies on the action of the RhoA interaction partner and regulator Dia1." (PMID 18941507, 2008). "For instance, TGF-β stimulates EMT in cancers of the breast and other tissues by activating phosphoinositide 3-kinase, Akt, RhoA, p160(ROCK), and p38 mitogen-activated protein (MAP) kinase." (PMID 16168131, 2005). "Therefore, the overall antitumor effect of RHOA pathway inhibitors likely results from combined direct effects on cancer cells and indirect modulation of the TME." (PMID 41362935, 2025). "Our study demonstrates that mechanical stretching significantly upregulates the expression of the protein biomarkers RhoA and Rac1 in clinical cancer samples and cancer cells, with a clear correlation between increased biomarker levels and advanced cancer stages." (PMID 39887960, 2025).